MMP9 (matrix metallopeptidase 9)
Diseases named in the same sentence as MMP9 in open-access papers (continued):
Sharing a sentence is not in itself a finding about the gene and the disease.
liver cancer (continued). "In the current study, silencing of FASN, FSCN1 or SPTBN1 expression in liver cancer cells led to changes in the mRNA expression of EMT-associated markers, E-cadherin, N-cadherin, vimentin and transcription factors Snail and Twist, and altered the protein expression of MMP-2 and MMP-9." (PMID 32699531, 2020). "However, PtoxPdp as a dithiocarbamate derivative repressed MMP-2, and MMP-9 expression in the liver cancer cell line was first observed, this indicated that the structural unit of podophyllotoxin introduced to dithiocarbamate did not alter action pattern in regulation of MMPs." (PMID 31557166, 2019). "In summary, our work provides the first evidence that rhFNHN29 and rhFNHC36 may play an important role in safeguarding against human liver cancer through the reduction of integrin expression level and MMP-9 activity and may shed light on a novel strategy for liver cancer therapy." (PMID 20939933, 2010). "Further, we knocked down or overexpressed CREB5 in a mouse liver cancer cell line Hep1-6 and found that CREB5 promoted EMT and increased the expression of MMP2 and MMP9 in Hep1-6 cells." (PMID 39915455, 2025). "In liver cancer, the MIDN/CTNNB1/MMP9 axis promotes progression through inducing a suppressive tumour immune microenvironment." (PMID 40111059, 2025). "They reached the same conclusion that HIF-1α can promote the progression of liver cancer by affecting MMP2 and MMP9." (PMID 40563539, 2025). "For instance, in liver cancer, aberrant activation of the PI3K/PTEN/Akt/mTOR pathway upregulates matrix metalloproteinase 9 (MMP-9), contributing to tumor invasion and metastasis." (PMID 40704062, 2025). "The occurrence, development, and immune escape mechanism of liver cancer are closely related to the production of sMICA/B mediated by MMP2 and MMP9." (PMID 40563539, 2025). "In, 2013, it was reported that the addition of exogenous HMGB1 to H22 liver cancer cells, acting on RAGE and through the NF-kB pathway, increases the expression of matrix metalloproteinase 9 (MMP9), promoting the invasion of H22 cells." (PMID 38529373, 2024). "FAK deletion inhibited liver cancer metastasis by reducing the expression and activity of matrix metalloproteinase 2 (MMP-2) and matrix metalloproteinase 9 (MMP-9)." (PMID 38560575, 2024). "A total of 86 targets of the herbal compound for liver cancer were obtained, mainly five core targets of IL-6, ESR1, JUN, IL1β, and MMP9." (PMID 37680619, 2023). "Although no experimental data pertaining to AGAP11 have been reported in the field of cancer, there is evidence to suggest that closely related genes, namely, LPL, MMP9, SGK1, TLR4, and FOS play certain roles in liver cancer through different mechanisms." (PMID 36726348, 2023). "The MTT method was used to detect the proliferation, migration, and invasion capabilities of the two groups of liver cancer cells (LCC) and to explore the effect of lncRNA-PVT1 on rat LCC by regulating the expression of MMP9." (PMID 36164442, 2022). "At present, anti-CD147 monoclonal antibody can inhibit the invasion ability of liver cancer by reducing the expression of MMP2 and MMP9." (PMID 35003362, 2021). "In our study, we found that PP2 treatment in liver cancer cells suppressed cell migration and invasion, accompanied by downregulated expression of MMP2/MMP9, suggesting they were responsible for the suppression effect of PP2." (PMID 31988091, 2020). "In liver cancer, the PI3K/PTEN/Akt/mTOR pathway activated is involved in tumor invasion and metastasis by up-regulating matrix metallopeptidase 9 (MMP-9)." (PMID 32175074, 2020). "The CXCR3-A isoform bound by CXCL9 upregulates MMP2 and MMP9 expression, and promotes invasion and metastasis of CD133(+) liver cancer cells." (PMID 31623313, 2019).
liver cancer (continued). "MMP2, MMP9 and MMP13 proteins play significant roles in liver cancer invasion and migration." (PMID 39744479, 2025). "In addition to the EMT regulated by Snail, nuclear Snail was also reported to play an another key role in regulating cell invasion by inducing increases in MMPs, such as MMP-1, MMP-2, MMP-7, MMP-9, and MMP-14, in ovarian, oral, and liver cancers." (PMID 36766694, 2023). "In liver cancer, FXR overexpression results in a significant reduction in the total and nuclear β-catenin proteins and its downstream target genes, including c-Jun and MMP9, in vitro and in vivo that contribute to the inhibition of cell invasive abilities." (PMID 35563650, 2022). "For example, in pancreatic and liver cancers under irradiation, fibroblasts increase the secretion of various humoral factors including cytokines such as bFGF, TNF-a, VEGF, IL-6, EGF, MMP-2, and MMP-9." (PMID 35089951, 2022). "Whether ASIC1α can inhibit the migration, invasion, and proliferation of liver cancer by inhibiting MMP-2 and MMP-9 via the PI3K/AKT/mTOR pathway is unknown." (PMID 35840921, 2022). "Recent studies revealed the inhibition of MMP9 which is regulated by α1-ACT, could suppress liver cancer development." (PMID 34671598, 2021). "Our results showed that morphine could suppress malignant behavior of liver cancer cells by up-regulation of the OGFR and down-regulation of MOR, uPA and MMP-9." (PMID 33968773, 2021). "Taken together, these results suggest that NRF2 MTs increase MMP9 promoter activity in HCC cells, which might contribute to the invasiveness of liver cancer." (PMID 34069882, 2021). "Furthermore, Fascin-1 knockdown suppressed MMP-2 and MMP-9 expression, impaired actin cytoskeleton rearrangement, inactivated Hippo/YAP signaling, and increased Sorafenib sensitivity in liver cancer cells." (PMID 34897283, 2021). "Moreover, after Mettl3 knockdown in liver cancer cells, Western blot analysis validated that Mettl3 knockdown decreased the protein level of Snail, MMP2, MMP9, and FN1, but increased that of E-Cad, in both HepG2 and MHCC97H cells." (PMID 32483411, 2020). "We further revealed inhibited liver cancer cell migration and invasion through suppressed cofilin activity, as well as downregulation of the AKT/NF-κB signaling pathway resulted in a decrease MMP-2/MMP-9 expression by PP2 treatment." (PMID 31988091, 2020). "In HBV-related HCC, the axis of HBx- (NF-kB)-(CXCL9/CXCR3-A)-pERK1/2-MMP2/MMP9 may play an important role in the invasion and migration of CD133+ liver cancer cells." (PMID 26883105, 2016). "In the study, CXCR3-A isoform that was bound by CXCL9 was found to cause significant change of ERK1/2 phosphorylation level in the MAPK signaling pathway, consequently upregulating the MMP2 and MMP9 expression and promoting invasion and metastasis of CD133+ liver cancer cells." (PMID 26883105, 2016). "In previous study, we found that BMP-2 silence could inhibit liver cancer cell’s proliferation, migration and invasion by down-regulation of MMP2 and MMP9 through MAPK/ERK pathway." (PMID 27886213, 2016). "In previous study, we found that BMP-2 could promote liver cancer cell’s proliferation and migration, and played an important role in liver cancer invasion through down-regulation of MMP2 and MMP9." (PMID 25002834, 2014). "However, the relationship between ASIC1α and MMP-2 and MMP-9 in liver cancer cells has not been elucidated." (PMID 35840921, 2022). "In addition, OPE exhibited anti-migration and anti-invasion effects on liver cancer cells, which might be related to decreased expression of MMP-2 and MMP-9." (PMID 32021647, 2020). "In this study, the mRNA expression of integrins and MMPs that was detected in different liver cancer cell lines and MHCC97H cells was found to feature low levels of integrin α5 mRNA expression and high levels of integrin αv, integrin β1, integrin β3, MMP1, MMP2 and MMP9 mRNA expression." (PMID 20939933, 2010).
liver cancer (continued). "Thus, GXI might inhibit metastasis of liver cancer via MMP-7 and MMP-9 inhibition." (PMID 31569691, 2019). "It was noted that the expression of matrix metalloproteinase 9 (MMP9), an important marker of migration, adhesion, invasion and metastasis of liver cancer, was higher in HCC tumors in mice lacking specific AR in the liver (L-AR−/y) compared to WT-animals." (PMID 32290381, 2020).
breast tumor (85 papers, 2008 to 2026). "MMP-9, MMPs with gelatinase activity, are highly expressed in invasive breast tumours, promote tumour cell migration and are associated with poor prognosis." (PMID 39156102, 2024). "On the other hand, decreased MMP-9 levels in breast tumors are associated with tissue fibrosis, a common finding in this disease." (PMID 35163668, 2022). "Positive MMP9 expression is significantly associated with higher grade breast tumours (grades II and III)." (PMID 25605249, 2015). "It was reported that overexpression of MMP-9 is associated with increased invasiveness of ovarian and breast tumors, which may lead to decreased survival in patients." (PMID 29337896, 2018). "CCR7, EZR, IDH2 and MMP9 were highly expressed in breast tumor tissues, whereas they were expressed at low levels in normal breast tissues (p < 0.001)." (PMID 38438469, 2024). "The results showed that CCL5 and IDH2 were not significantly differentially methylated in BRCA, while CCR7, EZR, IL8, and IL2RG were hypermethylated in normal tissues, and FLT3, MAPK10, and MMP9 were hypermethylated in breast tumor tissues." (PMID 38438469, 2024). "It epigenetically regulates the expression of MMP9 and β-catenin, inhibiting proliferation and metastasis in breast tumors and inverting the epithelial-to-mesenchymal transition, respectively." (PMID 39858410, 2024). "Taken together, these results demonstrated the specific binding of CREKA-GK8-QC to MMP-9 and fibronectin in breast tumor tissues." (PMID 36978072, 2023). "Statistical analysis demonstrated that the expression levels of MMP-9 in breast tumors were higher (~ 7.33-fold, **p < 0.01) than those in normal breast tissues." (PMID 36978072, 2023). "Western blot analysis clearly indicated that MMP-9 and fibronectin were both overexpressed in the breast tumor tissues." (PMID 36978072, 2023). "We found that higher MMP-9 and fibronectin expression levels were detected in orthotopic breast tumors than in normal breast tissues." (PMID 36978072, 2023). "The immunohistochemistry staining analysis also showed that Gpt2 knockout markedly reduced GABA synthesis, PKC and CREB activation, and MMP9 expression in mouse breast tumors." (PMID 36923530, 2023). "Different factors such as Hypoxia, HIF-1α, HER2, and matrix metalloproteinase 9 (MMP-9) increase the expression of VEGF in BC, and VEGF is associated with angiogenesis in breast tumors." (PMID 36849958, 2023). "For instance, FAK promoted the invasion of 4T1 murine breast tumor cells increasing the expression and secretion of matrix metallopeptidase 9 (MMP9) and the urokinase plasminogen activator (uPA)." (PMID 33562737, 2021). "Elevated production of functional MMP2 and MMP9 was detected in breast tumor cells following CXCL12 stimulation, in the context of CXCR4 expression." (PMID 32582148, 2020). "Further analysis revealed IL-6, CCL2, and MMP9 were upregulated in breast tumors with low compared to high IGF-1R." (PMID 30458886, 2018). "The results demonstrated that TET-CSOSA/Cela significantly suppressed Bcl-2 activation of lung metastatic cells and reduced MMP-9 expression of 4T1 breast tumor cells by blocking NF-κB." (PMID 29355035, 2018). "TGFBI-expressing cells were found to inhibit tumor cell invasion through the downregulation of MMP-2 and MMP-9 in lung and breast tumor cells." (PMID 30453668, 2018). "Data from a study that isolated RNA from breast tumors using laser capture microdissection (LCM) revealed an 8-fold increase in MMP9 levels (Richardson Breast, )." (PMID 28423685, 2017). "As a whole, our data firmly establish Rab40b as a major regulator of targeted MMP2 and MMP9 secretion and breast tumor growth and metastasis in vivo and in vitro." (PMID 27789576, 2016). "In the breast tumor samples it has been observed that, tumors, expressing higher level of uPA and MMP9, express less amount of E–cadherin." (PMID 26906973, 2016).
breast tumor (continued). "Based on the in vitro cell culture study along with the evidence of the expression correlation in breast tumor tissue, the present investigation clearly shows the simultaneous inhibition of uPA and MMP9 can inhibit tumor invasion and aggressiveness." (PMID 26906973, 2016). "As for the production site of MMP-9 in breast tumors, our results suggest that carcinoma cells are the main source of MMP-9 given that adjacent stromal cell consistently exhibited a much weaker degree of expression." (PMID 25151367, 2014). "Low levels of MMP-9 expression were detected in the cytoplasm of cancer cells in both luminal A and B breast tumors." (PMID 25151367, 2014). "The source of MMP9 found in human breast tumors has been seen to have significant bearing on its prognostic interpretation." (PMID 24811362, 2014). "Additional roles for fibronectin in promoting tumour cells are suggested by data demonstrating that proteolytic processing of fibronectin induces breast tumour cell motility, invasion and activation of MMP-9." (PMID 19173736, 2009). "Furthermore, we analyzed the expression levels of MMP-9 and fibronectin through western blot in the breast tumors and normal breast tissues of orthotopic 4T1 breast tumor-bearing mice." (PMID 36978072, 2023). "Amorim and colleagues recently showed that extracellular vesicles released by breast tumor cells are associated with TAN polarization towards a pro-tumoral N2 phenotype, characterized by the expression of CD184, IL-8, VEGF, and MMP-9, thereby sustaining chronic inflammation." (PMID 36289899, 2022). "Among MMPs, MMP-2 and MMP-9 are involved in breast tumor invasion." (PMID 36016682, 2022). "Although the invasive capacity of tumor cells appears to be unaffected by the presence of collagen fibril network in the invasion test, the expression levels of critical EMT markers, MMP-2 and MMP-9 have been shown to change when breast tumor cells are cultured in the presence of type I collagen." (PMID 30736469, 2019). "Overall, the partial screening of hydrolytic activity confirms the presence of thrombin (with or without PRP supplementation), trypsin-like serine proteinases, MMP-2 and MMP-9 metalloproteinases, and cathepsin-cysteine proteinases in the secretome of breast tumor cells." (PMID 28187434, 2017). "Finally we have reviewed our model in the breast tumor samples expressing the different level of uPA and MMP9." (PMID 26906973, 2016). "TF-triggered PAR-2 signaling also results in increased MMP-9 expression, which positively correlates with the invasiveness of MCF-7 breast tumor cells and may be linked to MMP-9 response to arachidonic acid metabolism." (PMID 26573921, 2015). "Based on these findings, we suggest that breast tumor cells that express high levels of MMP-9 may be more invasive and have a greater probability of passing through the extracellular matrix and entering the lymphatic system." (PMID 26656588, 2015). "Its antitumorigenic effects were elicited through an inhibition of COX-2, matrix metaloproteinase-9 (MMP-9), and NFκB activation in breast tumor, since the enzymes MMP-9 and COX-2 are involved in the tumor metastasis, and NF-κB mediates tumor cell proliferation." (PMID 26180596, 2015). "Furthermore, among all specimens of the small group (30 breast tumor specimens) examined, TSP50+/MMP9+ tumors were also associated with a higher metastasis rate and poor patient survival." (PMID 25811800, 2015). "In gelatinase B/MMP-9 knockout mice, impaired vascularisation associates with reduced pericyte-recruitment and vascular pericytes have been shown to express gelatinase B/MMP-9 in human breast tumours." (PMID 24473089, 2014). "Evidence suggests that MMP-9 plays a significant role in breast tumor cell invasion and metastasis." (PMID 23407024, 2013).
breast tumor (continued). "Since several prometastatic genes (Plau, Mmp2, Mmp9, Has2, and Has3) were downregulated in Mbd2-KO PyMT tumors, we next used formalin-fixed lung tissue sections collected at the experimental endpoint and stained them with hematoxylin and eosin (H&E) to assess breast tumor metastasis to the lung." (PMID 38556549, 2024). "Similarly, patients could also be taking anti-estrogens such as tamoxifen or fulvestrant, both of which have been shown to increase MMP2 and MMP9 secretion from breast tumor cells." (PMID 36765529, 2023). "In addition, Huang and his colleagues demonstrated that pyropheophorbide-α methyl ester-mediated PDT could suppress the migration/invasion of breast tumor by inhibiting Akt-NF-κB-dependent MMP-9 expression via ROS." (PMID 36482460, 2022). "Loss of PAR3 in breast tumors also caused mislocalization and activation of atypical PKC, which triggered JAK-dependent activation of STAT3 and induction of matrix metalloproteinase 9 (MMP9) to promote destruction of the extracellular matrix, invasion, and metastasis." (PMID 26682247, 2015). "SOD2, iNOS, MMP2, MMP9 were evaluated through western blot and TUNEL test preformed for breast tumor." (PMID 39503169, 2024). "The complex formation of glycoprotein CD44 and its ligand MMP-9 on the cell surface of breast tumor cells was found to promote ECM degradation, cell migration, invasion and metastasis, suggesting that the MMP-9/CD44 axis is a promising therapeutic target." (PMID 37185776, 2023). "CTSG can also activate pro-MMP-9 to cut and release active transforming growth factor β (TGF-β), MMP-13, and RANKL at the tumor-bone interface of osteolytic lesions induced by breast tumors." (PMID 35935989, 2022). "For instance, IL-1β promoted breast tumor cell invasion through the activation of the Src/FAK signaling pathway and MMP-9 production." (PMID 33562737, 2021). "Breast tumor cells excrete zinc-dependent proteases such as MMP-2 and MMP-9, which damage an integral part of the basal membrane, type IV collagen, resulting in cancer cells’ entry into the systemic circulation." (PMID 34535685, 2021). "With regards to TIMP2:MMP expression, breast tumors seemed to be more consistent with an almost ubiquitous increase in MMP11 and a smaller number of patients exhibiting high MMP9 expression." (PMID 31882975, 2019). "In breast tumor D3H2LN cells, AngII upregulates MMP-2 / MMP-9 and ICAM1, which are involved in cell adhesion, migration, and invasion." (PMID 29179450, 2017). "Meanwhile, the MMP family are actively connected with biological changes, such as embryogenesis, and bone regeneration, from which MMP-9 and MMP-2 particularly works in the breast tumor." (PMID 29371992, 2017). "Especially, (58/90) 64% of breast tumors of pathologic grade III were TSP50+/p65+, and (57/90) 63% were TSP50+/MMP9+." (PMID 25811800, 2015). "This study is devoted to investigate the clinical significance of IL-12 expression in BC and to deduce its correlation with CA15-3, CEA, MMP9, TIMP1 as breast tumor markers." (PMID 27275301, 2015). "In summary, the results of this study demonstrate that NGENCuB is more effective than NGEN inhibiting cell proliferation, migration and pro-MMP9 activity, and inducing apoptosis in MDA-MB-231 breast tumor cells." (PMID 25192075, 2014). "In ER+ breast tumors E2 exerts a protective role since it regulates the expression both of MMP-2 and MMP-9 as well as syndecan-4 and, therefore, limits the ability of cells to invade the adjacent tissues." (PMID 23936773, 2013). "IL-17-dependent invasion of breast tumours was blocked by a range of selective MMP antagonists for MMP-2, MMP-3 and MMP-9 as well as a broad-spectrum MMP antagonist." (PMID 19014637, 2008). "In our study we did not observe statistically significant correlation of MMP-9 with the size of primary breast tumors (T)." (PMID 27110764, 2016).